STOML2 (stomatin like 2)
Description:
Mitochondrial protein that probably regulates the biogenesis and the activity of mitochondria. Stimulates cardiolipin biosynthesis, binds cardiolipin-enriched membranes where it recruits and stabilizes some proteins including prohibitin and may therefore act in the organization of functional microdomains in mitochondrial membranes. Through regulation of the mitochondrial function may play a role into several biological processes including cell migration, cell proliferation, T-cell activation, calcium homeostasis and cellular response to stress. May play a role in calcium homeostasis through negative regulation of calcium efflux from mitochondria. Required for mitochondrial hyperfusion a pro-survival cellular response to stress which results in increased ATP production by mitochondria. May also regulate the organization of functional domains at the plasma membrane and play a role in T-cell activation through association with the T-cell receptor signaling complex and its regulation.
Synonyms: SLP-2; HSPC108
Tractability: Antibody: UniProt places it where antibodies can reach, with high confidence; its Gene Ontology location is reachable by antibodies, with high confidence; the Human Protein Atlas places it where antibodies can reach. PROTAC: ubiquitination databases record sites on it; its protein half-life has been measured.
Gene: Protein-coding gene on chromosome 9 (35,099,606 to 35,103,195, reverse strand). Ensembl gene ENSG00000165283.
Subcellular location: Cell membrane; Mitochondrion; Mitochondrion inner membrane; Mitochondrion intermembrane space; Membrane raft; Cytoplasm, cytoskeleton
Subcellular location (Human Protein Atlas): Cytosol; Plasma membrane
Pathways (Reactome):
Cellular responses to stimuli: Cellular response to mitochondrial stress
Transport of small molecules: Processing of SMDT1
Gene Ontology:
Molecular function: cardiolipin binding; GTPase binding; protein binding; T cell receptor binding
Biological process: intracellular calcium ion homeostasis; mitochondrion organization; protein complex oligomerization; T cell receptor signaling pathway; CD4-positive, alpha-beta T cell activation; lipid localization; mitochondrial protein processing; positive regulation of interleukin-2 production; stress-induced mitochondrial fusion; proton motive force-driven mitochondrial ATP synthesis
Cellular component: actin cytoskeleton; cytosol; immunological synapse; membrane raft; mitochondrial inner membrane; mitochondrial intermembrane space; mitochondrion; plasma membrane; cytoskeleton; membrane
Genetic constraint (gnomAD): Loss-of-function variants: 22 observed, 47.31 expected, observed/expected ratio (o/e) 0.47, 90% interval 0.33 to 0.66. The upper end of that interval is the gene's LOEUF score, 0.66, which puts it in group 2 of 6, group 1 being the genes least tolerant of losing a copy. Missense variants: 359 observed, 495.05 expected, observed/expected ratio (o/e) 0.73, 90% interval 0.66 to 0.79. Synonymous variants: 181 observed, 195.24 expected, observed/expected ratio (o/e) 0.93, 90% interval 0.82 to 1.05.
Homologues: Orthologues: chimpanzee STOML2 (100% identical), macaque STOML2 (99% identical), dog STOML2 (98% identical), pig STOML2 (98% identical), rabbit STOML2 (96% identical), guinea pig STOML2 (95% identical), mouse Stoml2 (94% identical), rat Stoml2 (94% identical), tropical clawed frog stoml2 (75% identical), zebrafish stoml2 (71% identical), Drosophila melanogaster Stoml2 (59% identical), Caenorhabditis elegans stl-1 (54% identical). Paralogues in human: STOML3 (24% identical), STOM (22% identical), NPHS2 (21% identical), STOML1 (18% identical).
Diseases named in the same sentence as STOML2 in open-access papers:
STOML2 is named in the same sentence as 33 diseases in open-access papers, as found by Europe PMC text mining. Sharing a sentence is not in itself a finding about the gene and the disease. The quoted sentences say what the papers report.
hepatocellular carcinoma (6 papers, 2021 to 2024). A malignant tumor that arises from hepatocytes. "The difference in gene mutation and expression between hepatocellular cancer cells and pancreatic cancer cells might contribute to the distinct role of STOML2 in mitophagy." (PMID 36906621, 2023). "STOML2 was reported to potentiate metastasis of hepatocellular carcinoma by promoting PINK1-mediated mitophagy and regulating sensitivity to Lenvatinib." (PMID 36531021, 2022). "For example, through regulating PINK1-mediated mitophagy, STOML2 was found to promote cancer metastasis and lenvatinib resistance in hepatocellular carcinoma." (PMID 34774067, 2021). "In hepatocellular cancer, STOML2 could directly bind with PINK1 and promote its subsequent mitophagy, which is different from our present study in pancreatic cancer." (PMID 36906621, 2023). "Stomatin-like protein 2 (STOML2) interacts with and stabilizes PINK1, amplifying PINK1/Parkin-mediated mitophagy, which in turn promotes the growth and metastasis of hepatocellular carcinoma (HCC)." (PMID 39416788, 2024). "Similarly, IHC was performed on HCC samples from 80 clinical patients, resulting in a malignant degree of hepatocellular carcinoma, lower CYB5A and LC3 expression levels, and higher STOML2 and p-STAT3 expression levels." (PMID 35851063, 2022).
pancreatic cancer (4 papers, 2019 to 2025). "Based on the proteomic data of 140 pancreatic cancer cases, there was a significant positive association between STOML2 and PARL at the protein level (P = 0.02, R = 0.24)." (PMID 36906621, 2023). "Considering the development of targeted drug delivery, it is possible to construct engineered exosomes with exogenous nucleic acids encoding STOML2 or STOML2 protein that could deliver them to pancreatic cancer cells in patients." (PMID 36906621, 2023). "Moreover, the association between STOML2 expression and overall survival (OS) time in pancreatic cancer patients was explored via Kaplan‒Meier analysis." (PMID 36906621, 2023). "STOML2 stabilizes PARL and prevents gemcitabine-mediated PINK1-dependent mitophagy to reduce the chemoresistance of pancreatic cancer, making STOML2-targeted therapy as a potential strategy for gemcitabine sensitization." (PMID 39035027, 2024). "Considering that STOML2 expression has a strong relationship with the prognosis of pancreatic cancer patients, we further tested the function of STOML2 in GEM resistance, which is the first-line chemotherapy against pancreatic cancer." (PMID 36906621, 2023). "Because the expression of full-length PINK1 was low in the general state, we employed carbonyl cyanide m-chlorophenylhydrazone (CCCP) (10 μM) to elevate PINK1 levels, making it suitable to observe the effects of STOML2 on PINK1 in pancreatic cancer cells." (PMID 36906621, 2023). "To assess the expression of STOML2 in pancreatic cancer and its relationship with overall survival, we analysed STOML2 expression via the TCGA database." (PMID 36906621, 2023). "STOML2 was inhibited by small interfering RNA (siSTOML2) and overexpressed by an overexpression plasmid (STOML2 OE) in pancreatic cancer cell lines (PANC1 and BxPC3)." (PMID 36906621, 2023). "In this study, using a tissue microarray (TMA), we found that high STOML2 expression was correlated with higher survival of patients with pancreatic cancer." (PMID 36906621, 2023). "We further employed clinical samples and tested the STOML2 protein levels in pancreatic cancer tissues by a tissue microarray (TMA)." (PMID 36906621, 2023). "The results supported that STOML2 was highly expressed in pancreatic cancer tissues compared with their paired neighboring normal pancreas tissues." (PMID 36906621, 2023). "The results suggested that STOML2 was primarily located in the mitochondria of pancreatic cancer cells." (PMID 36906621, 2023). "Hence, STOML2 was remarkably highly expressed in pancreatic cancer, which indicated a good prognosis in pancreatic cancer patients." (PMID 36906621, 2023). "In addition, we found that STOML2 was positively related to mitochondrial mass and negatively related to mitophagy in pancreatic cancer cells." (PMID 36906621, 2023). "Meanwhile, the proliferation and chemoresistance of pancreatic cancer cells could be retarded by STOML2." (PMID 36906621, 2023). "Simultaneously, STOML2 inhibited autophagic flux in pancreatic cancer, which might contribute to chemoresistance in pancreatic cancer." (PMID 36906621, 2023). "Previous studies have suggested that STOML2 promotes the progression of multiple malignant tumors, including liver cancer, head and neck squamous cell carcinoma, ovarian cancer, colorectal cancer, and even pancreatic cancer." (PMID 36906621, 2023). "Another report showed that STOML2 could upregulate the hexosamine biosynthetic pathway and promote pancreatic cancer metastasis." (PMID 36906621, 2023). "Compared to normal pancreatic tissue, STOML2 was highly expressed in pancreatic cancer." (PMID 36906621, 2023). "In this study, we reported that STOML2 was highly expressed in pancreatic tumor tissue but related to longer survival, which might support the idea that mitophagy could repress tumorigenesis but promote cancer progression." (PMID 36906621, 2023). "Therefore, the function and mechanism of STOML2 in pancreatic cancer deserve further study." (PMID 36906621, 2023).
pancreatic cancer (continued). "Interestingly, the apoptosis in STOML2-overexpressing pancreatic cancer cells with antioxidant treatment was still higher than that in the blank control groups, which indicated that there might exist other ways to induce mitophagy-related apoptosis." (PMID 36906621, 2023). "Therefore, STOML2 could effectively restrict mitophagy in pancreatic cancer cells, which might mediate its role in reducing chemoresistance and prolonging OS in pancreatic cancer patients." (PMID 36906621, 2023). "Therefore, overexpression of STOML2 might be a novel anticancer strategy for pancreatic cancer treatment." (PMID 36906621, 2023). "Therefore, STOML2 could inhibit the proliferation and chemoresistance of pancreatic cancer cells." (PMID 36906621, 2023). "Thus, STOML2 could effectively reduce the chemoresistance of pancreatic cancer in vivo." (PMID 36906621, 2023). "In conclusion, our study found that STOML2 could repress PINK1-induced mitophagy by directly stabilizing PARL, thus inhibiting pancreatic cancer chemoresistance." (PMID 36906621, 2023). "In both PANC1 and BxPC3 cells, the STOML2 antibody could also pull down PARL, which suggested that STOML2 could directly bind and stabilize PARL in pancreatic cancer cells." (PMID 36906621, 2023). "In conclusion, STOML2 could stabilize PARL and promote PINK1 degradation, which represses mitophagy and ultimately reduces chemoresistance in pancreatic cancer." (PMID 36906621, 2023). "First, we only analysed STOML2-overexpressing pancreatic cancer cells in vivo, which lacked data from the STOML2 downregulation group." (PMID 36906621, 2023). "Therefore, STOML2 might repress mitophagy and increase functional mitochondrial mass, potentially decreasing GEM resistance in pancreatic cancer cells." (PMID 36906621, 2023).
breast carcinoma (3 papers, 2024 to 2025). "While, other phosphoproteins (e.g., BTN1A1, KRT10, HECTD3, NSD3, and STOML2) were associated with human breast cancer prognosis." (PMID 40839607, 2025). "High STOML2 levels are associated with breast cancer progression and poor prognosis." (PMID 40839607, 2025). "In human breast cancer, high expression levels of KRT10, HECTD3, NSD3, and STOML2 were associated with unfavorable outcomes, whereas high BTN1A1 expression was linked to a better prognosis." (PMID 40839607, 2025). "Similarly, chlortetracycline exhibited the most stable binding with STOML2 and was found to reduce the invasive properties of breast cancer cells." (PMID 39991825, 2025). "A recent study found that STOML2 promotes the viability and motility of breast cancer cells in vitro by mediating FOXO3a expression and the extracellular signal-regulated kinase (ERK) pathway, indicating its potential as a therapeutic target for breast cancer." (PMID 40839607, 2025).
cervical cancer (3 papers, 2020 to 2021). A primary or metastatic malignant neoplasm involving the cervix. "Previous studies revealed the prognostic role of STOML2 protein in different cancer types including cervical cancer." (PMID 32682359, 2020). "Moreover, upregulation of STOML2 has been identified in many cancers, including gastric adenocarcinoma, glioma and cervical cancer, indicating a role of STOML2 in cancer progression." (PMID 34774067, 2021).
colorectal cancer (3 papers, 2021 to 2024). A primary or metastatic malignant neoplasm that affects the colon or rectum. "STOML2 was significantly overexpressed in colorectal cancer and was associated with unfavorable prognoses." (PMID 40453362, 2024). "STOML2 was significantly overexpressed in colorectal cancer and its elevation was associated with unfavorable prognosis." (PMID 34781982, 2021). "Given the role of STOML2 in modulating the expression PD-L1 in colorectal cancer cells, we next assessed the potential benefit of Stoml2 in tumor treated with immune checkpoint blockage (ICB)." (PMID 38214751, 2024). "This study demonstrated that in colorectal cancer, STOML2 expression is elevated and interacts with PHB through activating MAPK signaling pathway, to promote proliferation both in vitro and in vivo." (PMID 34781982, 2021). "Knockdown of STOML2 suppressed proliferation of colorectal cancer, thus attenuated subcutaneous and orthotopic tumor growth, while overexpressed STOML2 promoted proliferation in cell lines and organoids." (PMID 34781982, 2021). "This research aims to reveal regulatory mechanism of STOML2 and to provide evidence for clinical therapeutics, via exploration of its role in colorectal cancer, and identification of its interacting protein." (PMID 34781982, 2021). "Furthermore, knockdown of STOML2 downregulated phosphorylation of RAF1, MEK1/2, and ERK1/2 on the MAPK signaling pathway, indicating common pathway activated by STOML2 and PHB in colorectal cancer proliferation." (PMID 34781982, 2021).
gastric adenocarcinoma (2 papers, 2014 to 2021). "High expression of STOML2 is also associated with poorer survival in gastric adenocarcinoma, and metastasis and poor survival in lung cancer 28,46." (PMID 25060540, 2014).
glioma (2 papers, 2021 to 2024). A benign or malignant brain and spinal cord tumor that arises from glial cells (astrocytes, oligodendrocytes, ependymal cells). "Studies have also shown that suppression of STOML2 reduces IL-6 expression in glioma by inhibiting the transcription of NF-κB." (PMID 38214751, 2024).
liver cancer (2 papers, 2021 to 2025). An epithelial or non-epithelial malignant neoplasm that arises from the liver. "We discovered potential drugs for three proteins associated with liver cancer: ASS1 (arginine, aspartic acid, and citrulline), KRT8 (ambroxol, diltiazem, and amikacin), and STOML2 (chortetracycline, chlorzoxazone, and dirithromycin)." (PMID 39991825, 2025). "Additionally, feature plots and violin plots were generated for the tier 1 and tier 2 proteins ASS1, KRT8, and STOML2 and the liver cancer marker gene AFP." (PMID 39991825, 2025). "For external validation, we utilized liver cancer GWAS outcome data from a different cohort (ieu-b-4953) to validate the three MR proteins ASS1, KRT8, and STOML2, which presented the highest posterior probability in the colocalization analysis." (PMID 39991825, 2025). "In a single-cell liver cancer dataset, ASS1, KRT8, and STOML2 were expressed mainly in hepatic progenitor cells and malignant cells, with KRT8 predominantly found in hepatic progenitor cells and playing a role in the oncogenesis of malignant liver cells." (PMID 39991825, 2025).
multiple myeloma (2 papers, 2019 to 2021). "This study aimed to investigate the effects of STOML2 and the relationship between STOML2 and PAI-1 in the development of multiple myeloma (MM)." (PMID 34774067, 2021). "Thus, this study aimed to investigate the effects of STOML2 and the relationship between STOML2 and PAI-1 in the development of multiple myeloma (MM), providing a new prognostic marker and therapeutic target for MM." (PMID 34774067, 2021).
ovarian carcinoma (2 papers, 2022 to 2023). A malignant neoplasm originating from the surface ovarian epithelium. "PHB2 and STOML2 are both reportedly overexpressed and attributed to the mitochondrial function and apoptosis resistance in ovarian cancer." (PMID 37190120, 2023). "In summary, the breakdown of the PHB2/STOML2 complex promotes apoptosis of ovarian cancer cells through the mitochondrial PHB2/OMA1/DELE1 pathway." (PMID 37190120, 2023). "Exploring other proteases that bind to the PHB2/STOML2 complex will provide more in-depth mechanistic insights into the roles of PHB2 and STOML2 in mitochondrial homeostasis and chemosensitivity of ovarian cancer." (PMID 35163244, 2022). "Exploring the regulation of OMA1 by the PHB2/STOML2 complex will help to illustrate a potential mechanism of targeting mitochondria to increase the chemosensitivity of ovarian cancer cells." (PMID 35163244, 2022). "Therefore, exploring the relationship between the sublocalization of PHB2 and STOML2 and their functions will help to further illustrate their roles in the chemosensitivity of ovarian cancer." (PMID 35163244, 2022). "PHB2 and STOML2 are reportedly overexpressed in ovarian cancer, which is related to mitochondrial function and apoptosis resistance, but the mechanism remains unclear." (PMID 35163244, 2022).
Alzheimer disease (1 paper, 2017). A progressive, neurodegenerative disease characterized by loss of function and death of nerve cells in several areas of the brain leading to loss of cognitive function such as memory and language. "Additionally, we demonstrate that some of these dysregulations, such as diminished DLP1 levels and its mitochondrial localization, as well as reduced STOML2 and MFN2 fusion protein levels, take place in fibroblasts from sporadic Alzheimer's disease patients." (PMID 29201274, 2017).
dysplasia (1 paper, 2014). A usually neoplastic transformation of the cell, associated with altered architectural tissue patterns. "Furthermore, lentiviral-mediated overexpression of VCP, DCTN3, and STOML2 in Cal-27 and POE9n-tert, OSCC and dysplasia cell lines with neutral DNA copy number at 9p13, enhanced both proliferation and anchorage independent growth." (PMID 25060540, 2014).
esophageal cancer (1 paper, 2020). A primary or metastatic malignant neoplasm involving the esophagus. "Suppression of STOML2 in esophageal cancer cells reduced the growth rate and cell attachment." (PMID 32682359, 2020).
gastric cancer (1 paper, 2021). A primary or metastatic malignant neoplasm involving the stomach. "Following discovery of overexpression of STOML2 in gastric cancer and investigation into specific molecular mechanism of this gene afterwards, we were intrigued whether STOML2 presented similar overexpressed profile and oncologic effect in CRC." (PMID 34781982, 2021).
head and neck squamous cell carcinoma (1 paper, 2021). A squamous cell carcinoma that arises from any of the following anatomic sites: lip and oral cavity, nasal cavity, paranasal sinuses, pharynx, larynx, and salivary glands. "Recent related studies also implied that, STOML2 modulated tumor malignancy via IL6-STAT3 pathway in head and neck squamous cell carcinoma." (PMID 34781982, 2021).
hepatitis B (1 paper, 2021). "These patients, among which 186 cases (81.9%) showed liver cirrhosis with hepatitis B background, were divided into high or low STOML2 expression groups according to the immunostaining scores." (PMID 33446239, 2021).
laryngeal squamous cell carcinoma (1 paper, 2014). A squamous cell carcinoma that arises from the larynx. "STOML2 has been described as a positive regulator of cancer cell growth; its increased expression is associated with esophageal precancers and its expression has been reported as increasing with invasive disease stages in laryngeal squamous cell carcinomas 24,26." (PMID 25060540, 2014).